GLP1R (glucagon like peptide 1 receptor)
Diseases named in the same sentence as GLP1R in open-access papers (continued):
Sharing a sentence is not in itself a finding about the gene and the disease.
Stroke (135 papers, 2012 to 2026). Sudden impairment of blood flow to a part of the brain due to occlusion or rupture of an artery to the brain. "Gene expression data within GLP1R was associated with the lead variant genotypes for BMI, chronic pain and stroke." (PMID 39838854, 2025). "Increasing evidence has demonstrated that GLP-1R agonists exhibit a favorable benefit/risk profile and reduce the risk of myocardial infarction, stroke, cognitive disorder, and cardiovascular death." (PMID 39456499, 2024). "Further studies have found that T2DM patients who were treated with GLP-1R agonists were at reduced risk for developing AD or PD and were protected against stroke." (PMID 39062586, 2024). "Two meta-analyses have further shown that GLP-1R agonists reduced 12–13% of cardiovascular mortality, 12% of all-cause mortality, 6–9% of myocardial infarction, and 13–14% of stroke." (PMID 38255878, 2024). "SGLT2 inhibitors have exhibited better effects regarding a reduced incidence of HF, whereas GLP-1-R agonists have shown a reduced risk of CV events, particularly stroke." (PMID 37623335, 2023). "There are limited data on head-to-head comparative risk of stroke between sodium-glucose cotransporter 2 inhibitors (SGLT2i) and glucagon-like peptide-1 receptor agonists (GLP-1RA)." (PMID 36829226, 2023). "Dilation of cortical arterioles induced by GLP-1R activation is likely to lessen the impact of the neurotoxic effects associated with impaired cerebral perfusion in stroke, as early improved perfusion is beneficial for better functional outcomes." (PMID 33942194, 2021). "GLP1R agonists were associated with a statistically significant reduction in rates of stroke (HR: 0.87, 95% CI: 0.76 to 0.98, P = 0.023); the number needed to treat was 209 person-years’ exposure to treatment." (PMID 30223891, 2018). "So, it provided a potential clinical use of GLP-1R agonists for the treatment of stroke in T2D patients or individuals at high risk to suffer from a stroke (e.g. pretreatment strategies)." (PMID 26863436, 2016). "We hypothesised that greater weight loss by co-activation of GLP-1R/NPY2R would have a greater effect on post-stroke recovery than semaglutide monotherapy." (PMID 41094027, 2026). "Importantly, both interventions improved functional recovery after stroke to a similar extent, without affecting infarct size, indicating that enhanced stroke recovery by GLP-1R and NPY2R activation occurs entirely via weight loss." (PMID 41094027, 2026). "Furthermore, specific trials such as SUSTAIN-6 and LEADER showed substantial reductions in stroke risk with GLP-1R agonist (GLP-1RA) treatment." (PMID 39148946, 2024). "Moreover, we recently showed that the post-stroke administration of the GLP-1R agonist Exendin-4 restored vascular remodeling after stroke, in association with improved recovery." (PMID 38424560, 2024). "GLP-1 RA (glucagon-like peptide-1 receptor agonists), including semaglutide, may reduce stroke risk in people with type 2 diabetes." (PMID 35582947, 2022). "The picture remains essentially the same with reduced cardiovascular and all cause mortality but neutral effects on stroke incidence (semaglutide in SUSTAIN-6 being the only GLP-1R agonist with significant effect on stroke incidence) by GLP-1R agonists and neutral results by DPP-4i." (PMID 29466979, 2018). "Finally, we show that the same pharmacological strategies that are efficacious in improving stroke recovery through pre-stroke weight loss (via GLP-1R/NPY2R) can additionally provide acute neuroprotective effects post-stroke, independently of weight loss induction." (PMID 41094027, 2026). "Recent animal studies suggest that weight loss induced by a diet change or pharmacologically (via the activation of the glucagon-like peptide 1 receptor) also improves functional outcome after stroke." (PMID 41877181, 2026).
Stroke (continued). "Glucagon-like peptide-1 receptor agonists (GLP-1RAs) reduce major adverse cardiovascular events, including stroke, in high-risk cardiometabolic populations, but their association with outcomes in asymptomatic ICAS is yet to be evaluated." (PMID 42188698, 2026). "Numerous large-scale clinical trials suggest that GLP-1R agonists have the potential to reduce stroke incidence, although the precise mechanism remains under intensive investigation." (PMID 39148946, 2024). "Evidence from these trials, with stroke as a secondary endpoint, along with real-world data, suggests potential benefits in stroke prevention, particularly with glucagon-like peptide 1 receptor agonists." (PMID 38791064, 2024). "A very recent study found that giving rodents glucagon-like peptide-1 receptor agonists (GLP-1RAs) lowers the amount of d-ROMs in their blood after they have had a stroke." (PMID 38539887, 2024). "Noteworthily, the 2020 Canadian Best Stroke Practices endorse GLP-1-R agonists for individuals with T2DM who already experienced a stroke and still have not achieve the HbA1C target." (PMID 37623335, 2023). "Altogether, GLP-1-R agonists demonstrate a significant neuroprotective effect and, therefore, should be used as an effective and safe drug in stroke prevention strategies." (PMID 37623335, 2023). "Recent studies indicate that drugs targeting the glucagon-like peptide-1 receptor (GLP-1R) have neuroprotective effects against stroke." (PMID 35370875, 2022). "The activation of GLP-1R exerts neuroprotection in some animal models of Alzheimer’s diseases, Parkinson’s diseases, and stroke." (PMID 35359227, 2022). "Schematic representation of the cell signaling pathways that are activated by GLP-1R stimulation and that exert the neuroprotection against insults that modeled stroke." (PMID 35370875, 2022). "In terms of stroke, the most important new data have been obtained with glucagon-like peptide 1 receptor agonists (GLP-1RAs)." (PMID 34640636, 2021). "We further verified that Ex-4, a GLP-1R agonist, decreases stroke volume and HT by reversing the HG/LG-CD147 ratio and suppressing the activity of MMPs in vivo." (PMID 30953513, 2019). "The encouraging results of studies evaluating GLP1R agonists suggest that the protection from MI and stroke provided by these drugs derives from effects on the progression and destabilization of atherosclerotic plaques." (PMID 30250166, 2019). "PI3K/Akt is the most common downstream pathway of GLP-1R activation and was found to be activated by Ex-4 in many in vivo stroke models." (PMID 31779652, 2019). "In total, all these studies suggest that the administration of GLP-1 receptor (GLP-1R) agonists is one of the most promising treatments to pursue for patients immediately after stroke." (PMID 31721014, 2019). "Compared with the analysis by Liu and colleagues which only detected total mortality benefit of GLP1R agonists, we extended the benefits to cardiovascular mortality, stroke and the composite MACE." (PMID 30223891, 2018). "Recent randomized double-blind trials showed that treatment with GLP-1R agonists reduces cardiovascular events, stroke, and nephropathy." (PMID 29317623, 2018). "Several studies have shown the beneficial effects of GLP-1R activation on motor function in animal models of PD, HD and improved outcome after stroke." (PMID 27780892, 2016). "GLP-1Rs are highly expressed throughout the brain, and GLP-1 and GLP-1R agonists such as Ex-4 completely protect against glutamate–induced neuronal death and stroke injury." (PMID 27296974, 2016). "Our population-based study provided evidence for the potential CV benefits of treatment with the GLP-1R agonist exenatide, while used in combination with conventional anti-diabetic therapies in reducing risks of HF, MI and stroke in patients with T2DM." (PMID 25616979, 2015).
Stroke (continued). "We report that pre-stroke weight loss by GLP-1R activation, and more potently by dual co-activation of GLP-1 and NPY2 receptors, is a pharmacologically targetable mechanism, upstream of glycaemic regulation, through which post-stroke recovery is achieved." (PMID 41094027, 2026). "Only signals for chronic pain, stroke and BMI influenced expression of GLP1R." (PMID 39838854, 2025). "In stroke models, GLP-1R agonists reduce infarct size and edema, partly by dampening microglial/astrocyte inflammation and by direct neurotrophic support, e.g., GLP-1RA treatment decreases brain MPO (a neutrophil marker) and pro-inflammatory cytokines in ischemia." (PMID 41462689, 2025). "GLP-1R activation in the brain exerts neurotrophic and neuroprotective effects, demonstrating protective effects against various neurodegenerative conditions such as ischemia, stroke, Alzheimer's disease, Parkinson's disease, and brain trauma." (PMID 37822517, 2023). "In contrast, GLP-1-R agonists effectively reduce stroke events in patients with T2DM and established ASCVD, and thus have been implemented into recommendations for the stroke prevention of several associations, such as the American Stroke Association." (PMID 37623335, 2023). "Emerging evidence suggests that treatment with glucagon-like peptide-1 receptor agonists (GLP-1 RAs) could be an interesting treatment strategy to reduce neurological complications such as stroke, cognitive impairment, and peripheral neuropathy." (PMID 37231200, 2023). "The 2021 AHA/American Stroke Association Guidelines for the Prevention of Stroke in Patients with Stroke and Transient Ischemic Attack support the use of GLP-1-R as an addition to metformin in patients with T2DM and established ASCVD in order to reduce stroke risk." (PMID 37623335, 2023). "Glucagon-like peptide 1 receptor agonists and dipeptidyl-peptidase 4 inhibitors are very interesting in this respect since many preclinical studies have shown their positive effects on stroke recovery." (PMID 34937562, 2021). "Although potentially very interesting for the development of new strategies against stroke and neurodegenerative disorders, the mode of action of linagliptin in the brain is still largely unknown and seems to occur in a GLP-1R-independent manner." (PMID 31139140, 2019). "However, we recently showed that Linagliptin can improve stroke outcome independently from glycemia regulation and GLP-1R." (PMID 29776406, 2018). "Additionally, GLP-1R stimulation has been suggested to mediate neuroprotective effects in experimental stroke, Parkinson’s disease, and Alzheimer’s disease and to promote neurogenesis." (PMID 25822252, 2015). "Furthermore, confidence intervals for all null findings were wide (e.g., GLP1R: 95% CI 0.29–14) and thus do not rule out an effect of the drug mechanism on stroke risk." (PMID 39628323, 2024). "GLP-1 receptor (GLP-1R) agonists have shown neuroprotective effects in preclinical and clinical studies on neurodegenerative diseases in both the brain (e.g., Alzheimer’s disease, Parkinson’s disease, stroke and diabetic neuropathy) and the eye (e.g., diabetic retinopathy and AMD)." (PMID 35264926, 2022). "In addition to direct neuroprotective effects also supported by GLP-1R expression in neurons, the regulation of inflammation has been suggested as one potential mechanism since Ex-4 decreases the number of microglia after stroke." (PMID 25101679, 2014). "Moreover, GLP-1R expression has been reported present on glial cells during injury, and administration of Ex-4 in models of PD and stroke has been shown to reduce both glial cell activation and levels of proinflammatory cytokines, thereby diminishing neuroinflammation." (PMID 22384126, 2012). "We conclude that GLP-1R and NPY2R activation alone or in combination exhibit additional neuroprotective effects when administered acutely after stroke." (PMID 41094027, 2026).
Stroke (continued). "In stroke models, GLP-1RA therapy mitigates astrocyte-derived damage: experimental data show GLP-1R agonists reduce astrocytic release of MMP-9, IL-1, and IL-6 that otherwise disrupt the blood–brain barrier." (PMID 41462689, 2025). "Glucagon-like peptide-1 receptor agonists (GLP-1RA) (e.g., semaglutide, liraglutide) may also be of some benefit for patients with HF but their predominate role is in lowering the risk of stroke and peripheral artery disease and only modestly improving LVEF in HF patients." (PMID 41517552, 2025). "Research has shown that intracerebral administration of exendin-4 provides neuroprotection and improves locomotor activity after a stroke in rats, with these effects confirmed in GLP-1R knockout mice, indicating the involvement of GLP-1R." (PMID 39574978, 2024). "For the GLP-1R agonists, some of these studies have shown reduced cardiovascular mortality (LEADER employing liraglutide) and stroke incidence (SUSTAIN-6, employing semaglutide)." (PMID 29466979, 2018). "GLP-1R is widely expressed in the brain, and GLP-1R activation mediates neuroprotection in animal models of Alzheimer’s, Parkinson’s, Huntington’s, stroke and other degenerative diseases." (PMID 26863436, 2016). "Finally, GLP-1R and NPY2R activation can also improve stroke recovery through acute neuroprotection if they are given acutely after stroke, independently of their metabolic effects." (PMID 41094027, 2026). "Agents that increase GLP-1R signaling also appear to reduce the likelihood of developing diabetic retinopathy, AMD, cognitive dysfunction, motor dysfunction, stroke-induced neurodegenerative impairments, and neuropathy, supporting a potential neuroprotective effect of semaglutide in glaucoma." (PMID 35264926, 2022). "Of note, unlike SGLT2 inhibitors, treatment with GLP1R agonists resulted in significant protection from individual components of the composite outcome measure (MI and stroke) but was neutral in terms of rates of HF." (PMID 30250166, 2019). "Previous studies demonstrate that exendin-4, a GLP-1 receptor (GLP-1r) agonist, abrogates the severity of stroke in diabetic and non-diabetic rodent models." (PMID 29669555, 2018). "Clinical studies and meta-analyses show that GLP-1R agonists reduce the risk of major adverse cardiovascular events (MACE) by 10–14%, including cardiovascular mortality, nonfatal myocardial infarction, stroke and all-cause mortality, in patients with T2DM." (PMID 41303737, 2025). "Furthermore our previous study using mice lacking the GLP-1R showed that linagliptin can improve stroke outcome independently from GLP-1R." (PMID 29776406, 2018). "As a consequence, due to the total lack of clinical data addressing the potential efficacy of GLP-1R agonists and DPP-4i on functional parameters after stroke, functional outcome trials using these drugs are highly needed." (PMID 29466979, 2018).
chronic kidney disease (115 papers, 2013 to 2026). Impairment of the renal function secondary to chronic kidney damage persisting for three or more months. "American Diabetes Association recommended sodium-glucose cotransporter 2 inhibitors (SGLT2is) and glucagon-like peptide 1 receptor agonists (GLP-1RAs) for T2DM with chronic kidney disease (CKD) or high risk of chronic kidney disease treatment." (PMID 39246417, 2024). "Introduction and Objectives: There is limited evidence on the role of glucagon-like peptide-1 receptor agonists in the interplay between cardiovascular disease, chronic kidney disease, and metabolic dysfunction." (PMID 42075839, 2026). "As previous study reported renal tubular GLP-1R expression is reduced in chronic kidney disease, IHC staining of kidney sections was performed to explore GLP-1R protein expression." (PMID 35299724, 2021). "We previously reported that the GLP-1R agonist, exendin-4, attenuates muscle atrophy in dexamethasone-induced and chronic kidney disease-derived muscle atrophy models." (PMID 34537761, 2021). "Innovation in drug development often begins with foundational academic research, where breakthroughs sometimes arise serendipitously, as in the case of sodium-glucose cotransporter 2 inhibition and glucagon-like peptide-1 receptor agonism for chronic kidney disease (CKD)." (PMID 39611334, 2025). "The aim of this randomized controlled trial is to test the impact of the combination of glucagon-like peptide 1 receptor analogues/sodium-glucose cotransporter-2 inhibitors on body weight and kidney damage, in patients with type 1 diabetes and chronic kidney disease." (PMID 38365744, 2024). "Among the drugs that have been shown to slow the progression of chronic kidney disease are glucagon-like peptide 1 receptor agonists, sodium-glucose cotransporter-2 inhibitors, renin-angiotensin system inhibitors, and, more recently, non-steroidal mineralocorticoid receptor antagonists." (PMID 38012781, 2023). "If chronic kidney disease and heart failure predominate, sodium-glucose cotransporter-2 inhibitors and glucagon-like peptide-1 receptor agonists (GLP-1 RA) were recommended, as were basal insulin and sulfonylureas if A1c (glycated hemoglobin) exceeded the individual target level." (PMID 36628027, 2022). "We have reported that GLP-1R expression is enhanced by inhibition of GLP-1 degradation via dipeptidyl peptidase-4 (DPP-4) inhibition, and that GLP-1R activity is decreased in chronic kidney disease (CKD)." (PMID 31795376, 2019). "Robust evidence have demonstrated the beneficial effect of Sodium-glucose cotransporter-2 inhibitors (SGLT2i) and glucagon-like peptide-1 receptor agonists (GLP-1RA) in T2D patients with cardiovascular diseases and chronic kidney disease." (PMID 36277697, 2022). "Although glucagon-like peptide-1 receptor agonists (GLP-1RAs) and sodium-glucose co-transporter 2 inhibitors (SGLT2is) have demonstrated protective effects against chronic kidney disease, their impact on acute kidney injury (AKI) remains unclear." (PMID 42123715, 2026). "Newer GLMs, especially sodium glucose cotransporter-2 inhibitors (SGLT2is) and glucagon-like peptide-1 receptor agonists (GLP1RAs), have been increasingly prescribed to non-transplant patients with chronic kidney disease (CKD), with or without T2D." (PMID 39860655, 2025). "We examined the real-world comparative safety of sodium-glucose cotransporter-2 inhibitors (SGLT2i) vs. other newer anti-glycemic medications (dipeptidyl peptidase-4 inhibitors [DPP4i], glucagon-like peptide-1 receptor agonists [GLP1a]) in patients with and without chronic kidney disease (CKD)." (PMID 38993538, 2024).
chronic kidney disease (continued). "In addition to non-steroidal mineralocorticoid receptor antagonists, glucagon-like peptide-1 receptor agonists, used for select subpopulations with diabetic kidney disease, are the mainstay medical therapy for chronic kidney disease with the aim of improving long-term hard renal outcomes." (PMID 39451219, 2024). "Other medications (sodium-glucose cotransporter-2 inhibitors, glucagon-like peptide 1 receptor agonists, or GLP-1 RAs), with or without metformin, are appropriate initial therapy for individuals with T2DM or individuals at high risk of atherosclerotic CVD, heart failure, or chronic kidney disease." (PMID 36225474, 2022). "Renal GLP-1R activity is decreased in chronic kidney disease (CKD), but is increased by the inflammatory response; however, the effect of AKI on GLP-1R expression is unknown." (PMID 31795376, 2019). "Sodium-glucose co-transporter 2 inhibitors (SGLT2i), glucagon-like peptide-1 receptor agonists (GLP1a), and non-steroidal mineralocorticoid receptor antagonists (ns-MRA) are promising treatments for chronic kidney disease." (PMID 39858434, 2024). "For individuals with advanced chronic kidney disease (CKD), particularly those not undergoing hemodialysis, guidelines such as KDIGO prioritize the use of glucagon-like peptide-1 receptor agonists (GLP-1 RAs)." (PMID 38559691, 2024).